VCAN (versican)
Diseases named in the same sentence as VCAN in open-access papers (continued):
Sharing a sentence is not in itself a finding about the gene and the disease.
cancer (continued). "Mechanically, VCAN activates ECs and fibroblasts by activating TLR2, leading to a release of inflammatory cytokines, including tumour necrosis factor-alpha (TNFα), IL-6, and other proinflammatory cytokines, which promote neutrophil infiltration, angiogenesis, and cancer metastasis." (PMID 38791985, 2024). "Our research shows that low expression of VCAN can significantly improve the survival time of HCC patients, which implied that VCAN may be the downstream or upstream target of CSF1R in HCC, and is partly involved in its cancer-promoting effect." (PMID 35812745, 2022). "Specifically, ANLN, ARNTL2, TOP2A, PLAU, and VCAN expression are important in the invasion of the basement membrane, intravasation, extravasation, and colonization at secondary sites, but only TOP2A and ARNTL2 contribute to the survival of cancer cells while in circulation." (PMID 34591244, 2021). "Moreover, it correlated with cancer relapse, metastasis and unfavorable prognosis but the detailed CS composition of versican has not yet been studied in detail." (PMID 34201657, 2021). "Similarly, other classically identified molecules include VCAN and CD44 with their competing RNAs, endowed with complex roles in cell proliferation, invasive behaviors, and some other malignant signatures in contexts of cancer." (PMID 34659409, 2021). "Thus, the ability of the cancer cell to produce such a pericellular matrix, requiring CD44, HA, and versican (or aggrecan), could add to the chances of survival in the circulation." (PMID 26539408, 2015). "The proportion of responder for immunotherapy in the high VCAN group was significantly lower than the low VCAN group, and the AUC value of VCAN expression was higher than that of PD-L1, PD1 and CTLA4 expression, which suggested that VCAN might predict immunotherapy efficacy in other cancers." (PMID 36203562, 2022). "Moreover, our network analysis indicated alterations in MAPK/ERK and Jun-N-terminal kinase pathways and the potential important role of PAX3, VCAN, ARRB2, NR1H2, and ITGA5 that may provide insights into mechanisms involved in longevity and regeneration that are distinct from cancer." (PMID 22477361, 2013). "Upon separating these cancers by the detection of VCAN, it was found that TNBC demonstrated a statistically significant increase in the number epithelial % of CD8+ T cells in the absence of VCAN (p = 0.008); other subtypes demonstrated similar trends." (PMID 40361362, 2025). "Next, according to the mRNA expression level in various cancer types derived from the Cancer Cell Line Encyclopedia, the high mRNA expression of NCAN was almost unique to NB compared to other cancer cell types, whereas the expression of VCAN was not specific nor the highest in NB." (PMID 29290949, 2017).
infection (10 papers, 2016 to 2025). The state of being infected such as from the introduction of a foreign agent such as serum, vaccine, antigenic substance or organism. "The VCAN gene encodes the Versican protein, a binding protein crucial for tissue morphogenesis and extracellular matrix formation, which is integral to tissue inflammation in response to infection and tissue damage." (PMID 40309038, 2025). "In contrast, from days three to seven post-infection, there was significant upregulation of avidin (AVD), a biotin-binding protein, and versican (VCAN), which is linked to tissue remodelling and inflammation." (PMID 41472116, 2025). "We found that VCAN mRNA expression by HLFs was significantly suppressed following a 48-h infection with RSV (10-fold decrease, P < 0.0001)." (PMID 32047499, 2019). "Because the activation of this network of DAMPs leads to M1 innate immune responses, the down regulation of BGN, DCN, and VCAN during infection could effectively hinder the stimulation of the M1 (pro-inflammatory) mediators used in the current study." (PMID 28727780, 2017). "To enhance the rigor of this study and better understand which cells express versican in the lungs of control mice (day 0) and in mice infected with IAV (days 3 and 6 post-infection), we utilized an existing single-cell RNA sequencing (scRNA-seq) dataset." (PMID 40766376, 2025). "Following infection with RSV or mock infection with PBS, mouse lung histology was examined to observe the presence of HA, versican, and leukocyte sequestration." (PMID 33187989, 2021). "Compared with the control groups (no infection with P.a), the expression of VCAN was significantly increased in the one-hour and two-hour groups." (PMID 38685004, 2024). "Versican is not normally expressed in the healthy mature lung; however, it is rapidly induced during lung injury or infection." (PMID 33187989, 2021). "Thus, we propose that cleavage and removal of versican blockades via the action of proteoglycanases, such as ADAMTS5, is required for efficient T cell interaction with the ECM to encourage migration to effector sites in the periphery and for the subsequent resolution of infection." (PMID 27855162, 2016).
connective tissue disorder (5 papers, 2012 to 2022). A disease involving the connective tissue. "Whereas no previous associations have been reported between VCAN rs11726, BGN rs743641 or rs743642, and shoulder morbidity to date, other polymorphisms in BGN have been implicated in connective tissue disorders such as ACL ruptures." (PMID 34162438, 2021).
cardiovascular diseases (4 papers, 2009 to 2025). "A high turnover rate of the proteoglycan versican, represented by the increased presence of its fragmentation products in plasma, has previously been associated with cardiovascular diseases." (PMID 25354390, 2014). "This marker represents a fragmentation product of versican, an ECM proteoglycans implicated in vascular remodeling, and it was previously associated with cardiovascular diseases caused by dysregulated ECM turnover." (PMID 25354390, 2014). "Recent data suggest that CSPG2, also named VCAN (versican), modulates cell adhesion, proliferation, and migration, and plays a central role in the development and pathogenesis of several diseases, including cardiovascular diseases." (PMID 19196461, 2009).
adenocarcinoma (3 papers, 2020 to 2024). A common cancer characterized by the presence of malignant glandular cells. "The particular association of versican with patient outcome in adenocarcinoma, but not squamous NSCLC also suggests that its effects may be specific to the progression of the adenocarcinoma histological subtype." (PMID 33014869, 2020).
cardiac diseases (2 papers, 2019 to 2023). "Previous studies have demonstrated elevated levels of versican in some cardiac diseases, and it has been suggested to be involved in liver fibrosis." (PMID 38076279, 2023). "In a cardiac disease condition, either a combination of mechanical strain and cytokine stimulation, or the initial change in mechanical strain that occurs in cardiac diseases may induce versican synthesis." (PMID 38076279, 2023). "A number of studies have proposed the contribution of versican in ECM remodeling and heart disease, but the role of aggrecan (a cartilage proteoglycan with potential role in vascular stiffness), neurocan (specific to neuronal tissue), and brevican in heart disease remains unexplored." (PMID 31547598, 2019).
inflammation (2 papers, 2011 to 2020). Aberrant reaction of the microcirculation characterized by movement of fluid and leukocytes from the blood into extravascular tissues. "Conditional total knockout of versican in a mouse model of lung inflammation demonstrated significant reduction in leukocyte invasion into the lung and reduced inflammatory cytokine expression." (PMID 32265939, 2020). "Our main findings were the presence of epithelial denudation, airway inflammation and increased thickness of small airway walls with deposition of collagen I, fibronectin and versican, mainly localized to the outer wall." (PMID 21211006, 2011).
kidney disease (2 papers, 2012 to 2025). "Data on the association of versican expression with clinical outcome in kidney disease are scarce." (PMID 23024773, 2012). "The uncontrolled regulation of ECM components, such as collagens, proteoglycans, and glycoproteins (e.g. agrin, decorin, versican, biglycan, and laminins), has been described in numerous kidney diseases." (PMID 40524147, 2025). "To further characterize renal expression of versican isoforms and the association with clinical parameters we analyzed the expression of versican isoforms V0, V1, V2 and V3 in an independent cohort of 74 patients with various proteinuric kidney diseases." (PMID 23024773, 2012). "The results in humans were confirmed in three rodent models of kidney disease, in which renal versican expression was significantly upregulated as compared to corresponding controls." (PMID 23024773, 2012).
gastrointestinal tumors (1 paper, 2023). "Several studies have shown that CAFs secrete VCAN to promote the malignant phenotype of gastrointestinal tumors; high expression of VCAN is a high-risk factor for gastrointestinal tumor treatment resistance and poor prognosis." (PMID 37461061, 2023).
VCAN also shares sentences with these, for which no sentence is quoted: chronic obstructive pulmonary disease (5 papers); aortic aneurysm (4); Sepsis (4); brain tumors (3); depression (3); lymphoma (3); polycystic ovary syndrome (3); benign prostate hyperplasia (2); bipolar disorder (2); cataract (2); clear cell renal cell carcinoma (2); dissection (2); Ehlers-Danlos syndrome (2); Granuloma (2); multiple myeloma (2); oral squamous cell carcinoma (2); radicular cyst (2); Stickler syndrome (2); systemic sclerosis (2); acute lymphoblastic leukaemia (1); acute myocardial infarction (1); alopecia areata (1); anaplastic large cell lymphoma (1); anemia (1); aneurysmal disease (1); arterial tortuosity syndrome (1); atopic asthma (1); brain disorder (1); breast adenocarcinoma (1); bronchiolitis (1).
A further 62 diseases each share a sentence with VCAN in 1 paper.